CRP (C-reactive protein)
Diseases named in the same sentence as CRP in open-access papers (continued):
Sharing a sentence is not in itself a finding about the gene and the disease.
preeclampsia (continued). "The study found that CRP was significantly higher in preeclampsia groups in comparison to the control group and the increment was directly correlated with the severity of preeclampsia." (PMID 39280386, 2024). "Elevated levels of C-reactive protein (CRP) have been linked to pregnancy complications like gestational diabetes and preeclampsia." (PMID 38672972, 2024). "CRP, being a systemic inflammatory response marker, can be used as a valuable indicator for the progression of severity of preeclampsia, which is among the most problematic diseases of obstetrics." (PMID 39280386, 2024). "The study suggested that early CRP testing can be used as a marker for predicting the development of preeclampsia and complications like intrauterine growth restriction." (PMID 39280386, 2024). "The study found higher levels of CRP in cases compared with that of controls and the presence of a good correlation between CRP and preeclampsia." (PMID 39280386, 2024). "Elevated CRP levels in preeclampsia can be used as an indicator of progress of the disease and early prevention can be done." (PMID 39280386, 2024). "The study found that in severe preeclampsia, there are increased levels of CRP and decreased levels of platelets." (PMID 39280386, 2024). "There was also a significant difference between the mean levels of CRP in mild and severe preeclampsia (15.17±0.788 mg/L), (31.50±1.709 mg/L) compared with controls (4.79±0.178 mg/L), (P<0.01)." (PMID 36689404, 2023). "TNF-α and CRP levels were also significantly higher in preeclampsia than in the control group and normal pregnancy." (PMID 37700972, 2023). "This study suggested that CRP and CA-125 are biochemical markers that reflect the severity of the inflammatory process in preeclampsia." (PMID 36689404, 2023). "There were increased levels of CA-125, CRP and UA levels in women with preeclampsia which were correlated with the severity of the disease." (PMID 36689404, 2023). "In conclusion CA 125, CRP and UA were significantly higher in preeclampsia compared with the controls." (PMID 36689404, 2023). "The Receiver Operating Characteristic (ROC) curve of serum CA-125, CRP and UA in preeclampsia indicates the validity of these markers as sensitive and specific prognostic tools for the prediction of PE severity." (PMID 36689404, 2023). "C-reactive protein is an acute-phase protein of inflammation and is frequently studied as a marker of preeclampsia." (PMID 36034841, 2022). "Our L-NAME mouse model of preeclampsia demonstrates increased blood pressure, impaired foetal and placental growth, and increased circulating levels of ET-1, sFlt-1, and CRP." (PMID 35897759, 2022). "There was a significant increase of C-reactive protein in women with preeclampsia (p < 0.003) compared to controls." (PMID 36034841, 2022). "It has also been noted to effectively reduce the serum levels of MPO and hypersensitive C-reactive protein (hs-CRP) in patients with severe preeclampsia (PE)." (PMID 34790246, 2021). "Meta-analyses have described a potential association between preeclampsia and elevated levels of serum triglycerides, cholesterol, and inflammatory markers including CRP, IL-6, IL-8, and TNFα, some of which precede the onset of preeclampsia." (PMID 31590294, 2019). "In our cohort, a positive association between serum CRP levels and the development of maternal complications persisted even when maternal age, GDM, and gestational hypertension have been taken into consideration." (PMID 30533423, 2018). "The exact role of PCT and CRP in preeclampsia remains controversial, with the literature revealing conflicting accounts of their usefulness in predicting preeclampsia and its severity." (PMID 30079067, 2018). "CRP levels were similar between groups in early pregnancy, however, CRP levels were elevated in mid to late pregnancy in women who developed preeclampsia compared to women with who had uncomplicated pregnancy." (PMID 26104503, 2015).
preeclampsia (continued). "Pregnancy is a pro-inflammatory state where markers such as CRP are elevated; however, this process is exaggerated in women that subsequently develop preeclampsia and gestational diabetes." (PMID 26104503, 2015). "There was an association between CRP and systolic blood pressure, diastolic blood pressure, uric acid, ALP and AST in women with severe preeclampsia." (PMID 26113950, 2015). "The inflammatory markers, IL6, TNF α and CRP were significantly higher in the group with severe preeclampsia." (PMID 26113950, 2015). "This study reports a statistically significant difference in the levels of the pro inflammatory cytokines, IL 6 and TNF α and in CRP levels in the women with severe preeclampsia, compared with women with normotensive pregnancy." (PMID 26113950, 2015). "There is also evidence to suggest that the trajectory of CRP over the course of pregnancy is different in women who subsequently develop preeclampsia compared to women who have an uncomplicated pregnancy." (PMID 26104503, 2015). "This study reports increased levels of the inflammatory cytokines, IL6, TNF α and the marker of inflammation, CRP in severe preeclampsia." (PMID 26113950, 2015). "PM2.5 exposure has been associated with markers of systemic inflammation in humans that have been associated with preterm delivery, such as high-sensitivity C-reactive protein (CRP) and fibrinogen, and gestational hypertension." (PMID 24879653, 2014). "This included measurements of fMS-like tyrosine kinase and CRP which were elevated in the preeclampsia group compared with controls." (PMID 23690796, 2013). "The relationship of CRP levels and preeclampsia has already been studied and higher concentration of CRP has been reported during preeclampsia." (PMID 23826490, 2013). "Among pregnant women, a further elevation of CRP levels has been reported in pregnancies complicated by fetal growth restriction, preeclampsia, and preterm delivery." (PMID 22306530, 2012). "Next, we observed that a history of early-onset preeclampsia is related to higher plasma levels of CRP, fibrinogen and IL-6 at least six months after delivery." (PMID 18382655, 2008). "Median levels of CRP, fibrinogen, and IL-6 were significantly higher in women with a history of early-onset preeclampsia." (PMID 18382655, 2008). "To further evaluate the diagnostic performance of platelet indices, we conducted logistic regression analyses, which showed that IPF was the only variable independently associated with preeclampsia, whereas age, platelet count, MPV, PDW, BUN, and CRP lost significance in the multivariate model." (PMID 41515544, 2025). "The study also suggested that early diagnosis of preeclampsia is possible with the levels of CRP." (PMID 39280386, 2024). "In our study, the severity of preeclampsia increased with increasing levels of CRP." (PMID 39280386, 2024). "Furthermore, patients diagnosed with preeclampsia were separated into two subgroups: those with C-reactive protein (CRP) levels less than or equal to 0.1 mg/dL (n = 4) and those with CRP levels greater than or equal to 0.1 mg/dL (n = 4)." (PMID 38674031, 2024). "Additionally, one useful indicator of the severity of preeclampsia is CRP, a measure of systemic inflammation." (PMID 39280386, 2024). "This study concluded that by monitoring the value of CRP, it may be able to predict the progress of preeclampsia in pregnant women." (PMID 39280386, 2024). "We concluded that some inflammatory markers in our meta-analysis such as leptin, total cholesterol, triglycerides, TNFα and C-reactive protein were increased in pregnant women with preeclampsia compared to pregnant control women, so inflammatory markers are important markers of preeclampsia." (PMID 36034841, 2022).
preeclampsia (continued). "High levels of CRP in the first trimester have been reported, and more recently, it was shown that pregnant women with elevated CRP levels at 9 (±13) weeks were more likely to develop gestational diabetes mellitus and preeclampsia than pregnant women with lower levels." (PMID 35270396, 2022). "Elevated CRP is not just an early biomarker, but is likely a pathogenic factor contributing to preeclampsia by binding to phosphocholinated NKB and preferentially activating NK-3R." (PMID 34200131, 2021). "CRP levels are positively correlated with leptin levels in women with preeclampsia." (PMID 31914480, 2020). "Prepregnancy CRP levels were similar in women with preeclampsia and normotensive pregnancy." (PMID 30371249, 2018). "Also this study aims to determine the relationship, if any, between CRP levels and markers of organ damage (such as in the kidney and liver) in women with preeclampsia." (PMID 26113950, 2015). "The inflammatory cytokines, IL6, TNF α and CRP are elevated in severe preeclampsia and may mediate some of the clinical manifestations of the disorder." (PMID 26113950, 2015). "Neither of the loci has been previously shown to function in association with CRP, although mRNA expression of inflammation-related genes in leukocytes might be able to upregulate CDKN-1A, at least in preeclampsia." (PMID 25951190, 2015). "As a result of these controversies, we decided to measure the serum concentrations of IL-6, TNF α, and C reactive protein (CRP) in women with severe preeclampsia, and to determine if they differ from those of gestational age matched, normotensive, pregnant women." (PMID 26113950, 2015). "As well, women with preeclampsia in the 3rd trimester showed significantly higher levels of serum procalcitonin, C-reactive protein (CRP), and plasma D-dimer levels, and these hematological indices were significantly higher in patients with severe as compared to mild preeclampsia." (PMID 23690796, 2013). "In women with a history of early-onset preeclampsia significant positive correlations were observed between CRP, sICAM-1, fibrinogen and vWf, ranging from 0.20 for CRP and vWf to 0.38 for fibrinogen and vWf and for CRP and fibrinogen." (PMID 18382655, 2008). "The study was a prospective, nested, case-control study design where they evaluated serum levels of CRP concentrations using the competitive ELISA method in 506 women who maintained normotension throughout their pregnancy and 60 women who subsequently had preeclampsia." (PMID 39280386, 2024). "The current study's observation of a significantly higher level of CRP in the case group compared to the control group (P<0.001) is consistent with numerous prior studies where authors proposed that CRP is a promising biochemical marker that can indicate the severity of preeclampsia." (PMID 39280386, 2024). "Elevated CRP and NKB/NK-3R signaling contributes to the development of preeclampsia, and NKB/NK-3R signaling could be a therapeutic target and pathogenic biomarker for preeclampsia." (PMID 34200131, 2021). "This study is to determine the concentrations of IL-6, TNF α, and C reactive protein (CRP) in women with severe preeclampsia, and compare with those of gestational age- matched normotensive pregnant women and to correlate CRP levels with markers of organ damage in women with preeclampsia." (PMID 26113950, 2015). "Simultaneous measurement of leptin with C-reactive protein, several cytokines, chemokines, adhesion molecules and angiogenic factors in this study enabled us to investigate their relationship, which can help to understand the role of circulating leptin in normal pregnancy and preeclampsia." (PMID 21906313, 2011). "A recent comprehensive review indicates that most studies found women with preeclampsia exhibit elevated blood levels of cytokines (IL-6, IL-8, TNF-α, and C-reactive protein) compared to normotensive pregnant women." (PMID 41375625, 2025).
preeclampsia (continued). "Studies have consistently reported elevated levels of various cytokines in preeclampsia, including PGE2, TNF-α, IL-1, IL-6, and CRP." (PMID 38672972, 2024). "Coefficient of correlations (r) of cancer antigen (CA-125), C-reactive protein (CRP) and uric acid (UA) with mean arterial blood pressure (MAP) in preeclampsia." (PMID 36689404, 2023). "Elevated circulating levels of the potent vasoconstrictor ET-1, inflammatory marker CRP and anti-angiogenic factor sFLT-1 in our L-NAME model mirror the increase found in the circulation of individuals with preeclampsia." (PMID 36260752, 2022). "Compared with healthy group, the levels of serum Lp-PLA2, CRP, IL-6 and TNF-α in gestational hypertension group, mild preeclampsia group and severe preeclampsia group all increased." (PMID 35784937, 2022). "The role of inflammatory markers with elevated levels in preeclampsia has also been investigated, including the role of procalcitonin (PCT) and C-reactive protein (CRP)." (PMID 30079067, 2018). "Elevations in circulating leptin are associated to increased circulating levels of TNF-α in obese pregnant rats, and we have shown that women with preeclampsia have increased levels of TNF-α, IL-6 and C-reactive protein (CRP)." (PMID 30618843, 2018). "Although metformin reduced the levels of interleukin-6 (IL-6) and C-reactive protein (CRP), which are commonly elevated in preeclampsia cases, the incidence of pre-eclampsia was similar in both arms of the EMPOWaR study." (PMID 29082364, 2017). "In preeclampsia, the pro-inflammatory TNF-α and IL-6 and C-reactive protein are higher compared to normal pregnancy." (PMID 26247971, 2015). "This study reports a significant relationship between CRP and increasing blood pressure, uric acid, ALP and AST suggesting that inflammation is involved in the tissue damage that occurs in preeclampsia." (PMID 26113950, 2015). "Serum concentrations of CRP and ET-1 at 5 and 10 weeks postpartum were not significantly different between mice that had a normal pregnancy and mice that had a preeclampsia-like pregnancy." (PMID 40425613, 2025). "Only IPF retained an independent association with preeclampsia (OR = 27.29; p = 0.006), whereas age, platelet count, MPV, PDW, BUN, and CRP were not significant." (PMID 41515544, 2025). "IL-6, CRP and TNF-α in females with preeclampsia were elevated in comparison to the controls." (PMID 41394354, 2025). "Key terms included variations of “preeclampsia,” “pre-eclampsia,” “gestational hypertension,” and “toxemia” for the condition, alongside terms like “inflammation,” “inflammatory markers,” “cytokines,” “interleukins,” “TNF-alpha,” and “CRP” for the biomarkers." (PMID 40786291, 2025). "Mean CRP levels increased from preeclampsia without severe features (3.9 mg/dL), preeclampsia with severe features (5.2 mg/dL), and eclampsia (12.7 mg/dL) when compared with the respective control group (1.1 mg/dL, 1.16 mg/dL, and 1.2 mg/dL)." (PMID 39280386, 2024). "They revealed that recurrent preeclampsia was relevant with higher pre-pregnancy levels of C-reactive protein and fibrinogen than those without recurrent preeclampsia." (PMID 37658306, 2023). "Compared to the non-MetS group, the MetS group had a higher age, BMI by stage, parity, history of gestational diabetes (%), history of gestational hypertension (%), TC, TG, LDL, blood glucose, serum ferritin, hemoglobin, Hs-CRP, vitamin A, systolic pressure and diastolic pressure (P < 0.05)." (PMID 38053120, 2023). "It has been demonstrated that the expression of PTX3 in the peripheral blood is closely related to preeclampsia, but no such pregnancy complications has yet been firmly established for CRP." (PMID 34408755, 2021). "Raised CRP and PTX3 levels may indicate infection and preeclampsia, respectively." (PMID 34408755, 2021).
psychosis (75 papers, 2014 to 2026). "Specifically, interleukins (IL)-8, IL-6, IL-1β, TNF-α, and C-reactive protein (CRP) at various times of gestation have all been linked to an increased risk of psychotic disorders in offspring." (PMID 41073801, 2026). "Instead, associations between psychosis outcomes and baseline levels of CRP, IL-1RA, and sgp130 varied significantly by cannabis use status." (PMID 40813774, 2025). "Family history of psychotic disorders and certain inflammatory biomarkers, such as elevated C-reactive protein (CRP) and interleukin-6 (IL-6), have also been implicated in transition risk." (PMID 41254065, 2025). "The analysis unveiled a significant finding: individuals with elevated CRP levels at baseline exhibited a 50% higher risk of developing psychosis compared to those with lower levels." (PMID 39273641, 2024). "One study of people with psychosis found that self-reported low physical activity was associated with higher CRP levels." (PMID 39121088, 2024). "Key inflammatory markers that have been associated with postpartum psychosis are interleukin-8, monocyte chemoattractant protein-1 and c-reactive protein." (PMID 37139317, 2023). "A study revealed that significant inverse associations were found between CRP titers and delayed memory and attention, and also, data on psychosis and elevated CRP are limited." (PMID 37873776, 2023). "Elevated levels of CRP are linked to inflammatory processes in the body, making brain microvascular damage a significant contributing factor in developing psychotic disorders." (PMID 37803327, 2023). "The main inflammatory markers associated with clinical outcome in psychosis were interleukin (IL)-6, IL-10, and C-reactive protein (CRP)." (PMID 33679475, 2021). "It is important to note that CRP levels have been largely associated with cognitive symptoms in psychosis, while kynurenic acid levels are associated with psychiatric symptoms." (PMID 34884840, 2021). "Two of these studies examined the associations of childhood CRP levels with the risk of psychotic disorder in adulthood in the ALSPAC birth cohort." (PMID 34050185, 2021). "Our results suggest that high CRP levels at baseline (>3 mg/L) are associated with an increased risk of psychosis at follow-up." (PMID 34050185, 2021). "Our results suggest that evidence for an association between high, as compared to low, CRP levels at baseline and risk of psychosis at follow-up remained after adjusting for potential confounders." (PMID 34050185, 2021). "In future, further studies with a larger number of cases are required before definitive conclusions can be drawn about the longitudinal association between CRP and psychosis risk." (PMID 34050185, 2021). "We examined the prospective association between CRP levels and subsequent risk of developing a psychotic disorder by conducting a systematic review and meta-analysis of population-based cohort studies." (PMID 34050185, 2021). "While we provide some evidence of a longitudinal association between high CRP (>3 mg/L) and psychosis, larger studies are required to enable definitive conclusions." (PMID 34050185, 2021). "In this study, we meta-analyzed data from four population-based prospective studies comprising 89,792 participants and 494 incident cases of psychosis to examine the longitudinal associations between CRP at baseline and risk of psychosis at follow-up." (PMID 34050185, 2021). "Ligthart believes it is due to the conventionally accepted antimicrobial qualities of CRP that allow avoidance of childhood infections, which is one of the risk factors of developing psychosis." (PMID 34884840, 2021). "Meta-analyses of cross-sectional studies suggest that patients with psychosis have higher circulating levels of C-reactive protein (CRP) compared with healthy controls; however, cause and effect is unclear." (PMID 34050185, 2021). "A higher BMI has been associated with increased CRP levels, and BMI shows differential associations with psychosis risk depending on age." (PMID 34050185, 2021).